ARL5C (ARF like GTPase 5C)
Description:
Binds and exchanges GTP and GDP.
Synonyms: ARL12
Tractability: No criterion of Open Targets' tractability assessment is met for any kind of drug.
Gene: Protein-coding gene on chromosome 17 (39,156,894 to 39,167,484, reverse strand). Ensembl gene ENSG00000141748.
Gene Ontology:
Molecular function: GTP binding; GTPase activity
Biological process: intracellular protein transport; protein localization to Golgi membrane
Cellular component: trans-Golgi network
Genetic constraint (gnomAD): Loss-of-function variants: 23 observed, 23.51 expected, observed/expected ratio (o/e) 0.98, 90% interval 0.7 to 1.39. The upper end of that interval is the gene's LOEUF score, 1.39, which puts it in group 5 of 6, group 1 being the genes least tolerant of losing a copy. Missense variants: 199 observed, 235.38 expected, observed/expected ratio (o/e) 0.85, 90% interval 0.75 to 0.95. Synonymous variants: 71 observed, 85.48 expected, observed/expected ratio (o/e) 0.83, 90% interval 0.69 to 1.01.
Homologues: Orthologues: chimpanzee ARL5C (98% identical), mouse Arl5c (82% identical), dog ARL5C (78% identical), tropical clawed frog arl5c (65% identical), rat Arl5c (56% identical). Paralogues in human: ARL5B (68% identical), ARL5A (64% identical), ARF1 (42% identical), ARF3 (41% identical), TRIM23 (40% identical), ARF5 (40% identical), ARF6 (40% identical), ARL1 (40% identical), ARF4 (39% identical), ARL3 (38% identical), ARL2 (34% identical), ARL4A (34% identical), and 18 more.